MYCN (MYCN proto-oncogene, bHLH transcription factor)
Diseases named in the same sentence as MYCN in open-access papers (continued):
Sharing a sentence is not in itself a finding about the gene and the disease.
tumor (continued). "Moreover, ALK-F1174L expression, in mouse and zebrafish transgenic NB models, as well as in KI model, was not sufficient to initiate NB tumor formation in absence of MYCN co-expression or additional genetic alterations syntenic to that commonly found in human NB." (PMID 24947326, 2014). "Interestingly, stage 4 tumours without MYCN amplification may exhibit 1p22 and 1p34-p31 LOH in association with 11q and 14q loss, suggesting that losses in these 1p chromosomal regions are not mutually exclusive as for 1p36 LOH." (PMID 19192278, 2009). "Despite the presence of a MYCN amplification and absence of PDGFRA amplification, this tumor matched to the RTK1 subgroup." (PMID 40610013, 2026). "Neither of the primary tumours of pair 7 and 8 were reported to have MNA, which was also supported by low MYCN conumee-based estimates." (PMID 40713849, 2025). "In an inducible PAX3::FOXO1 human myoblast system, the fusion-oncogene cooperated with MYCN to inhibit differentiation and promote proliferation during transformation; however, in this context, PAX3::FOXO1 is not required for tumor recurrence." (PMID 40599857, 2025). "To gain deeper insights into the effects of tivantinib in NB, we established NB 3D spheroid tumor models using two NB cell lines, SH-SY5Y and IMR-32, representing MYCN non-amplified and amplified status." (PMID 39458991, 2024). "As expected, both MYCN and AURKA amplification in primary PC predict the transformation to t-NEPC, independent of other factors such as tumor stage, PSA levels, or GS." (PMID 38398199, 2024). "The tumor cells did not express CREBBP, but strongly expressed MYCN as expected based on their genotype." (PMID 37407554, 2023). "Compared with normal tissues, CENPA expression in tumor tissues was elevated in all three cell types; TIMP1 was elevated in stromal cells and decreased in malignant cells; MYCN expression levels were not significantly different in different cell types." (PMID 37213288, 2023). "Second, there is a lack of information on chemotherapy regimens, tumour recurrence, immunotherapy, targeted therapy, stem cell transplantation, INSS stage, monthly age and MYCN expansion." (PMID 37046344, 2023). "Principal component analyses of RNA-seq data derived from tumors and/or adrenal glands revealed no striking differences in respect to tumor location or between R26IGF2BP1 and R26IGF2BP1/MYCN tumors." (PMID 37246217, 2023). "Conversely, MYC and MYCN genes display very low correlation and show only a very modest induction in the BRAF- (vs RAS-like) tumour subgroup and are not differentially expressed in tumours vs healthy samples’ comparison." (PMID 37198319, 2023). "DCN-positive tumor staining was detected in about 13% of NB patient samples and correlated with age ≤18 months, with INSS stages 1–3, and a lack of MYCN-amplification." (PMID 36231134, 2022). "Finally, a comparison between MYCN‐high and ‐low tumour models with these treatments will help illuminate whether ferroptosis indeed represents a selective “Achilles' heel” for MYCN‐high tumours (or the triple combination can universally suppress tumour formation regardless of MYCN status)." (PMID 35908258, 2022). "In MYCN-amplified STA-NB-10 xenografts established in CD1:Foxn1nu/nu mice, continuous low-dose topotecan (0.1 mg/kg/day i.p. for 6 or 15 weeks) led to tumor regression and prolonged survival, with no evident toxicity." (PMID 36362482, 2022). "For 54 cases without additional HR characteristics (residual tumor > 1.5cm2, LCAMB, MYC amplification, MYCN amplification in other subgroups than Group 4), full molecular information was available for 22/45 patients ≥ 4 years and all nine patients < 4 years." (PMID 35190934, 2022). "Of note, MYCN-not-amplified NB and ASPS had the highest median TCR-β counts among the tumor types studied, in keeping with their responsiveness to immune therapy." (PMID 34818552, 2021).
tumor (continued). "The prognostic significance of the SCA and INRG markers in the whole cohort and that of the combination of tumor genomic patterns (GG-P2s and BP ≥ 7) with age at diagnosis and LDH in MYCN non-amplified, stage 4 NBs were confirmed." (PMID 35053166, 2021). "Both SR1078 and genetic overexpression of RORα effectively restore BMAL1 expression and oscillation, and block tumor growth in MNA, but not in non-MNA orthotopic xenografts, suggesting that the anti-tumor effect of SR1078 is MYCN-dependent." (PMID 34183658, 2021). "In this paper we document an in-depth study of spatial ITH, including several pieces of MYCN non-amplified (non-MNA), homogeneously amplified (MNA), and hetMNA primary HR-NB tumours." (PMID 34680323, 2021). "Of note, we found a tumor without RB1 alteration, it belonged to subtype 2 and displayed a high level of MYCN amplification (141 copies)." (PMID 34552068, 2021). "Despite being a target of MYCN transcription factor, VRK1 is a marker of tumor progression and malignancy independent of MYCN expression." (PMID 33233777, 2020). "According to the FISH results of tumor MYCN status, plasma MYCN/NAGK ratio was significantly higher in MYCN‐positive patients with NB than in negative patients, 69.07 (median CI 95%, 53.39, 142.50) vs 1.27 (median CI 95%, 1.00, 1.53)." (PMID 32896084, 2020). "More importantly, plasma MYCN/NAGK ratio is a promising, noninvasive, less time‐consuming, and repeatable method to check MYCN amplification of tumors in NB when tumor tissues are limited and MYCN nonamplification is detected in bone marrow cells by FISH test." (PMID 32896084, 2020). "Furthermore, in mouse allografts of SHH MB authors demonstrated uniform absence of MYCN, reduced proliferation and vascularity, as well as increase of apoptosis following in vivo treatment with PW-12, altogether resulting in a significant, more than five-fold decrease in tumor volume." (PMID 33585252, 2020). "More specifically, the proposed PNAs had the same sequence of tumor-suppressor miRNA-34a and were able to target 3'UTR MYCN mRNA through non-perfect base pairing as miRNAs do." (PMID 33330358, 2020). "Unlike the vague role of MYCN in FA metabolism, MYC was thought to play a key role in accelerating FA and cholesterol metabolism for sustainable tumor cell growth." (PMID 31856871, 2019). "Tumours treated with and without ATRA were analysed for changes in the differentiation markers and also for MYCN." (PMID 29301505, 2018). "For one tumor (T16), indeed no second RB1 hit or MYCN amplification was found by conventional DNA diagnostics (true negative)." (PMID 27126562, 2016). "We also aimed to define the potential anti-tumor and antiangiogenic effects of an anti-PlGF treatment in comparison to anti-VEGF treatments in a xenograft model of MYCN-nonamplified NB." (PMID 27669225, 2016). "Here, comparison of tumor and surrounding normal tissue verified MYCN, but not c-MYC mRNA expression in three of the nine tumors analysed, while neither MYCN nor c-MYC amplifications were detectable." (PMID 27769070, 2016). "In order to analyse the role of SCAs in infants with localised unresectable/disseminated NB without MYCN amplification, we have performed an array CGH analysis of tumours from infants enroled in the prospective European INES trials." (PMID 22146831, 2011). "Most interestingly, absence of polySia-NCAM-expressing tumor cells in TMA samples, however, was a strong unfavorable prognostic factor for overall survival in advanced disease (P = 0.0004), especially when MYCN was not amplified." (PMID 19222860, 2009). "To confirm that GSNO induces S-nitrosylation of MYCN, we employed a biotin-switch assay on protein lysates derived from tumor samples of mice treated with or without GSNO, which demonstrated the formation of S-nitrosylated MYCN upon GSNO treatment, specifically in the heavy chain of MYCN." (PMID 41198652, 2025).
tumor (continued). "In contrast to the Th-MYCN model, anti-GD2 therapy alone did not mediate a substantial anti-tumor effect though the addition of TETA produced a remarkable anti-tumor effect (median survival: 29 days vs. 19 days in Saline + anti-GD2, p = 0.0091) leading to durable eradication in ~40% of animals." (PMID 39668192, 2024). "In five cases with insufficient tumor material and in another case with no match in DNA methylation profiling, immunohistochemistry with antibodies against HOXB13 and MYCN proteins were used as surrogate markers for the methylation types of SP-MPE or SP-EPN-MYCN, respectively." (PMID 39713042, 2024). "In particular, T cells co-cultured with PBNP-PTT-treated SH-SY5Y (MYCN-non-amplified) and LAN-1 (MYCN-amplified) exhibited significantly higher cytotoxicity toward SH-SY5Y cells compared with LAN-1 cells, where minimal to negligible tumor cell killing by T cells was observed." (PMID 35326601, 2022). "Other tumor regions revealed some diffuse stainings of few TH+ positive cells with enlarged nuclei positive for MYCN, but negative for ALK (zoom 1), whereas other regions did not exhibit expression of TH, MYCN, and ALK (zoom 4)." (PMID 34493726, 2021). "Tumor types, such as stomach adenocarcinoma, lung adenocarcinoma, breast invasive carcinoma, and hepatocellular carcinoma, also exhibit frequent MYC amplification, but not that of MYCN and MYCL gene paralogs." (PMID 34503295, 2021). "However, in line with the lack of tumor formation in the brains of GL mice, we did not observe a significant increase in the abundance of selected Wnt and Shh targets (APC, GLI2, AXIN2, MYCN, MYC)." (PMID 34801069, 2021). "Interestingly, a previous in vivo study used a MYCN-amplified cell line in a xenograft model and found a PARP inhibitor did not affect tumour growth." (PMID 32577161, 2020). "In addition, we successfully used our workflow on sorted tumor cells from Tg(rag2:mMyc;rag2:GFP) or Tg(dβh:MYCN, dβh:GFP) adult zebrafish (data not shown)." (PMID 30894119, 2019). "Furthermore, unsupervised clustering with the top‐100 differentially expressed genes between MYCN‐high and MYCN‐low DTC samples separated tumors and DTCs by MYCN expression rather than cell type or tumor cell content." (PMID 28921546, 2018). "This putative negative correlation between the expression of MYC/MYCL/MYCN and HIF2A is supported by data retrieved from the databank of a published expression analysis of 81 SCLC tumor specimens showing that tumors with high pan-MYC expression generally express low levels of HIF2A (PMID: 26168399)." (PMID 28430666, 2017). "Collectively, these results provide new evidence that these three factors (Lig3, Lig1, and PARP1) have a functional role in MYCN oncogenic activity in human NCSC, and sets precedence to investigate alt-NHEJ and non-canonical DNA repair factors in NBL tumor initiation and progression." (PMID 29238067, 2017). "PlGF-blockade reduced tumor cell proliferation but did not affect endothelial microvessel density, while VEGF-blockade reduced microvessel density and induced some degree of vessel normalization in MYCN-unamplified SK-N-AS NBs." (PMID 27669225, 2016). "In addition, positive GALNT2 expression significantly correlated with younger age at diagnosis, early clinical stage, primary tumor originated from the extra-adrenal site, favorable INPC histology and MYCN non-amplification." (PMID 25362349, 2014). "MYCN-MB fusion transcripts were unique to each tumor; 2 recurrent fusion-partner genes, DDX1 and NBAS (immediately upstream of MYCN41) were involved in fusions with each other and additional partners (MYCNOS) in 3 MYCN-MBGrp3/4 tumors, but fusion position and gene order were not conserved." (PMID 39377358, 2025). "In view of the highly recurrent distal 2p gains in high-risk NBs this suggests that, in addition to increased expression levels of MYCN in cases of MYCN non-amplified tumors, an extra copy of the ALK gene and the gene for its ligand could impact tumor formation." (PMID 34945759, 2021).
tumor (continued). "Immunohistochemical staining of tumor sections with antibodies against pRb and phosphorylated Rb (ppRb) displayed high levels of pRb and ppRb in both RB1+/+ and RB1+/− tumors with MYCN amplification compared to no expression of these proteins in a classic RB1−/−, MYCN‐low tumor." (PMID 28211617, 2017). "The MYCN-amplified RB1-proficient hypermethylation-driven, differentially expressed genes are a functionally diverse set of genes, suggesting that hypermethylation in this tumor subtype is indeed not functionally unidirectional, and it may be modulating multiple aspects of the tumor biology." (PMID 36245757, 2022). "At the same time, there have been suggestions that amplification of the MYCN oncogene may affect the nature and function of the TME in NB tumors and that extracellular vesicles (EVs) represent a mechanism of communication between tumor cells and non-malignant cells in the TME." (PMID 33050533, 2020). "Importantly, in a long-term (>10 years) follow-up study, MYCN gene expression in HCC tumors was significantly higher in patients with recurrence than in those without recurrence and was positively correlated with the de novo recurrence of HCC with a single tumor but not with multiple tumors." (PMID 33937011, 2020).
cancer (595 papers, 2006 to 2026). A tumor composed of atypical neoplastic, often pleomorphic cells that invade other tissues. "Dysregulation of the MYCN-MAX complex is a hallmark of various cancers, making it an attractive therapeutic target." (PMID 39802403, 2025). "As with many cancers, miR-17 ~ 92 overexpression is frequently observed in NB, either through gene amplification or MYCN-mediated transactivation, where it is linked to poor prognosis." (PMID 40779030, 2025). "This work finds that ARID1A is a critical regulator of inflammatory signaling in NB and provides rationale for testing immune therapies in MYCN amplified NB that are effective in adult ARID1A mutated cancers." (PMID 40082458, 2025). "While MYC alterations are observed in a broad array of cancers, MYCN is especially implicated as a key factor in paediatric cancers originating from central and peripheral nervous system tissues." (PMID 40779030, 2025). "For instance, high-risk MYCN-amplified aggressive cancer cells express high levels of NEAT1_1 relative to NEAT1_2, while non-aggressive cancer cells with a more differentiated phenotype express relatively high levels of NEAT1_2." (PMID 40362651, 2025). "Patients with MYCN amplification are categorized as high‐risk NB due to the aggressive nature of these cancers." (PMID 39119816, 2025). "This discovery of MYCN's involvement in embryogenesis explains why dysregulated MYCN is linked to some embryonic signatures in MYCN-driven cancers." (PMID 39802403, 2025). "Sensitivity was related to MYCN status, a marker associated with adverse outcome across human cancers including WT." (PMID 39740515, 2025). "Here, we report that HGSC exhibits among the highest levels of MYCN expression and activity in human cancer, and this is strongly linked to diminished IFN type I signaling and antitumor immunity." (PMID 38748789, 2024). "The protein N-Myc, encoded by the MYCN gene, is associated with an elevated release of proteins, including cathepsin B, which in turn appears to enhance the invasiveness of cancer cells and their resistance to therapies." (PMID 39981299, 2024). "We found that HGSC exhibits among the highest levels of MYCN expression and transcriptional signature across human cancers, which is strongly linked to diminished features of antitumor immunity." (PMID 38748789, 2024). "In conclusion, the MYCN-associated lncRNA LOXL1-AS1 contributes to SHH-MB metastasis by promoting TGF-β2-mediated cancer stem-like phenotypes." (PMID 38689348, 2024). "Although NB is a highly heterogeneous cancer, its most common genetic alteration is the MYCN gene amplification, found in up to 50% of high-risk cases." (PMID 36982482, 2023). "Given the enormous number of cancers associated with differentiation, it is surprising that MYCN and other contemporary differentiation-related markers are not being widely used." (PMID 37745860, 2023). "Dysregulation of MYCN in cancers lead to aberrant MYCN oncoprotein levels and will cause dramatic transcriptional changes of its downstream genes, which subsequently promote the tumorigenesis." (PMID 37543638, 2023). "MYCN represents a critical oncogene, maintaining the tumorigenic state in several cancer types, implicated in cancer initiation, progression and invasion." (PMID 35739971, 2022). "SMAD9 knockdown attenuated the transcriptomic phenotypes of MYCN-associated autonomous nervous system development and the cancer cell cycle." (PMID 36539767, 2022). "MYCN amplification was identified as the first genetic biomarker of any cancer, specifically marking high-risk NB." (PMID 36290282, 2022). "High SMAD9 expression was associated with MYCN-associated autonomous neural tumorigenicity and a robust cancer cell cycle." (PMID 36539767, 2022). "MYCN overexpression is generally associated to poor prognosis, driving the cancer cells to a stem cell like phenotype, promoting growth, angiogenesis, and metastasis." (PMID 33718189, 2021).